STAT6 (signal transducer and activator of transcription 6)
Diseases named in the same sentence as STAT6 in open-access papers (continued):
Sharing a sentence is not in itself a finding about the gene and the disease.
acute respiratory distress syndrome (1 paper, 2022). Progressive and life-threatening pulmonary distress in the absence of an underlying pulmonary condition, usually following major trauma or surgery. "STAT6 has an immune suppressive role in the development of ALI and would be a promising therapeutic target in the treatment of ALI and possibly among patients with acute respiratory distress syndrome (ARDS)." (PMID 35606692, 2022).
allergic pneumonitis (1 paper, 2023). "This notion emphasized our results of the STAT6-associated M2 polarization in the allergic pneumonitis-only group and the possible p38-related M1 polarization in the combined model group." (PMID 37048067, 2023). "The IL-13, MUC5AC, STAT6, and p38 mRNA expression showed a significant rise (p < 0.001) in the allergic pneumonitis group when compared to the control gene values." (PMID 37048067, 2023). "Furthermore, pirfenidone was suggested as a viable treatment option that protected against CYP-induced steroid-resistant allergic pneumonitis via M1 macrophage polarization suppression by modulating IL-13/STAT6 and INF-γ/p38 pathways." (PMID 37048067, 2023). "Furthermore, CYP exposure in the allergic pneumonitis rats resulted in more increase (p < 0.003) in MUC5AC and p38 gene expression (respectively); meanwhile, the IL-13 and STAT6 (respectively) showed a further decrease (p < 0.05), in comparison to the allergic pneumonitis-only group." (PMID 37048067, 2023).
artery disease (1 paper, 2023). "Researchers found CFDP1 (along with YAP1 and STAT6) for HCAECs that passed the 5% false discovery level (FDR) correction at the gene level which associates CFDP1 with artery disease traits." (PMID 37566073, 2023).
autoimmune uveitis (1 paper, 2020). An autoimmune form of uveitis (disease). "It has been recently reported that MSCs suppressed DCs maturation via regulating the phosphorylation of Stat1 and Stat6 in experimental autoimmune uveitis." (PMID 32283569, 2020).
babesiosis (1 paper, 2023). Babesiosis refers to a condition caused by microscopic parasites that infect the red blood cells. "Low and similar level of STAT6 expression was found in dogs with advanced babesiosis (Babesia 2) and in dogs infected with D. repens." (PMID 36739305, 2023).
Behcet disease (1 paper, 2012). A chronic, relapsing, multisystemic vasculitis characterized by mucocutaneous lesions, as well as articular, vascular, ocular and central nervous system manifestations. "Behcet's disease is associated with a variant (rs1800871) that lies near the IL-10 promoter, adjacent to BRG1, STAT6 and CBP binding." (PMID 22336179, 2012).
Bone Tumors (1 paper, 2025). "In the 2020 WHO Classification of Soft Tissue and Bone Tumors, SFT is categorized as an intermediate fibroblastic neoplasm with low metastatic potential, defined by the NGFI-A binding protein 2 (NAB2)-signal transducer and activator of transcription 6 (STAT6) gene fusion." (PMID 41431481, 2025).
brain edema (1 paper, 2023). Increased intracellular or extracellular fluid in brain tissue. "Furthermore, treatment with 2′-FL maintained M2 microglial polarization through IL-4-induced STAT6 activation and IL-10 upregulation, which is crucial for the resolution of brain edema and recovery of motor behavior." (PMID 37372011, 2023).
brain injury (1 paper, 2015). Acute and chronic (see also brain INJURIES, CHRONIC) injuries to the brain, including the cerebral hemispheres, CEREBELLUM, and brain STEM. "Moreover, STAT6 has been described to inhibit JNK and NF-κB signaling pathways, which are critically involved in progression of ischemic brain injury." (PMID 26050199, 2015).
brain tumour (1 paper, 2022). "In this study, treatment with the STAT6 inhibitor AS1517499 was associated with a significant decrease in Arg1 expression in microglia and a significant reduction in brain tumour burden." (PMID 35359423, 2022). "Finally, inhibition of the anti-inflammatory microglial phenotype via STAT6 inhibition, in a model of haematogenously disseminated brain metastases, also significantly reduced brain tumour burden." (PMID 35359423, 2022).
celiac disease (1 paper, 2025). An autoimmune genetic disorder with an unknown pattern of inheritance that primarily affects the digestive tract. "a possible overlap in cytokine-mediated immune responses is suggested by STAT6, which is linked to cytokine signaling in NHL, and SH2B3, which is involved in immune control in Celiac disease." (PMID 40321894, 2025).
Chagas disease (1 paper, 2018). A parasitic infection caused by Trypanosoma cruzi. "So far, most studies addressing the function of IL-4Rα-mediated signaling in experimental Chagas disease employed IL-4-deficient(−/−) and STAT6−/− mice or neutralization of IL-4 by administration of monoclonal antibodies." (PMID 30555475, 2018).
chronic bronchitis (1 paper, 2026). A type of chronic obstructive pulmonary disease characterized by chronic inflammation in the bronchial tree that results in edema, mucus production, obstruction, and reduced airflow to and from the lung alveoli. "The study highlights the role of JAK/STAT signalling in COPD, with STAT3 linked to neutrophilic inflammation and STAT6 to eosinophilic inflammation and chronic bronchitis." (PMID 41846690, 2026).
Chronic colitis (1 paper, 2019). A chronic inflammatory disease of the large intestine (colon, cecum and rectum). "Loss of Stat6 rendered mice very susceptible to chronic colitis which caused significantly more weight loss in Stat6−/− mice compared to control mice after the second DSS cycle." (PMID 30353167, 2019).
chronic pancreatitis (1 paper, 2026). A chronic inflammatory process causing damage and fibrosis of the pancreatic parenchyma. "Our study demonstrates that the IL-4/IL-13 STAT6-signaling pathway represents a critical regulatory mechanism suppressing the inflammation and stimulating wound healing and organ regeneration during acute and chronic pancreatitis." (PMID 41486955, 2026). "However, deletion of STAT6 only moderately reduced the fibrosis during chronic pancreatitis." (PMID 41486955, 2026).
chronic rhinosinusitis with nasal polyps (1 paper, 2026). A type of chronic rhinosinusitis that is characterized by the presence of nasal polyps. "In a controlled experiment, SERPINB2 was found to be increased in eosinophilic chronic rhinosinusitis with nasal polyps (CRSwNP) nasal polyp epithelial cells and to promote T2 inflammation through STAT6 signaling, which could be considered a novel therapeutic target for CRSwNP." (PMID 41511918, 2026).
colon adenocarcinoma (1 paper, 2019). "In this study, four proprietary STAT6 specific small interfering RNA (siRNA) sequences were tested in vitro using the human colon adenocarcinoma cell line, HT-29, and the breast/duct carcinoma cell line, ZR-75-1." (PMID 31075146, 2019).
colorectal tumors (1 paper, 2024). "A previous study demonstrated that STAT6-deficient mice displayed fewer and smaller colorectal tumors compared to wild-type mice." (PMID 38554148, 2024). "Additionally, the STAT6 phosphorylation inhibitor AS1517499 significantly slowed the growth of colorectal tumors in mice when administered in combination with 5-FU." (PMID 38554148, 2024).
cryptococcosis (1 paper, 2019). An acute or chronic, localized or disseminated infection by Cryptococcus neoformans. "Therefore, blocking STAT6-mediated pathways in hematopoietic cells, including IM, does not appear to be sufficient to counteract the harmful effects of IM during acute cryptococcosis." (PMID 30897162, 2019). "To determine if more global blockade of M2 macrophage polarization pathways would reverse the detrimental host outcomes in our model of cryptococcosis, we generated STAT6-/- BM chimeras to knockout STAT6 in hematopoietic cells, since STAT6fl/fl mice are not commercially available." (PMID 30897162, 2019). "Interestingly, the conditional knockout of Arg1 in IM and the deletion of STAT6, a transcriptional regulator of Arg1, in hematopoietic cells could not reverse the impact of IM on host outcomes during acute cryptococcosis." (PMID 30897162, 2019).
cutaneous leishmaniasis (1 paper, 2012). Leishmaniasis affecting the skin. "Here we show that L. donovani induces host arg1 expression through a mechanism that involves parasite-induced STAT6 activation, but different from the prevailing paradigm of alternative activation in cutaneous leishmaniasis, occurs even in the absence of a polarized type 2 cytokine response." (PMID 22275864, 2012).
demyelination (1 paper, 2011). "To assess the possible involvement of host IL-2 in the HSV-IL-2-induced demyelination, we used BALB/c-STAT4−/− mice, which do not mount a TH1 response, and BALB/c-STAT6−/− mice, which do not mount a TH2 response." (PMID 21364747, 2011).
diabetic retinopathy (1 paper, 2026). "Phosphorylated IRF3 initiates signal transducer and activator of transcription 6 (STAT6) activation, amplifying IFN-β1 production, a process also observed in Toll-like receptor 4 (TLR4)-mediated blood–retinal barrier breakdown during diabetic retinopathy." (PMID 41487469, 2026).
Duchenne muscular dystrophy (1 paper, 2025). Duchenne muscular dystrophy (DMD) is a neuromuscular disease characterized by rapidly progressive muscle weakness and wasting due to degeneration of skeletal, smooth and cardiac muscle. "Contrary to prior data, this study shows that neither eosinophils nor STAT6-mediated IL-4/IL-13 signaling contribute significantly to muscle repair after acute injury or in Duchenne muscular dystrophy (DMD) models." (PMID 39900735, 2025).
ductal carcinoma in situ (1 paper, 2021). "In normal human breast tissues and ductal carcinoma in situ, expression patterns of IRS-1 correlate with those of STAT6 and p-STAT6." (PMID 34769439, 2021).
encephalitis (1 paper, 2016). An acute inflammatory process affecting the brain parenchyma. "Also, given that Stat6 phosphorylation is mediated by IL-4 and that IL-4-mediated inhibition of iNOS expression on macrophages is Stat6 dependent, we investigated the potential role of Stat6 in ROCV-induced encephalitis." (PMID 27334012, 2016).
endometrial cancer (1 paper, 2022). Primary or metastatic malignant neoplasm involving the endometrium (mucous membrane that lines the endometrial cavity). "This suggests that STAT5 and STAT6 may not be the factors that promote the development of endometrial cancer." (PMID 35244291, 2022).
esophageal squamous cell carcinoma (1 paper, 2023). Esophageal squamous cell carcinoma (ESCC) is a type of esophageal carcinoma (EC) that can affect any part of the esophagus, but is usually located in the upper or middle third. "In addition, miR-21-5p in EVs secreted in esophageal squamous cell carcinoma (ESCC) promoted the activation of M2 macrophages and exacerbated ESCC through the PTEN/AKT/STAT6 pathway." (PMID 37138859, 2023).
experimental autoimmune encephalomyelitis (1 paper, 2021). An autoimmune demyelinating disease of the central nervous system that is produced experimentally in animals by the injection of homogenized brain or spinal cord in Freund's adjuvant. "For example, in previous studies, GA was found to be protective against Experimental Autoimmune Encephalomyelitis (EAE) in Stat6–/– and IL4–/–IL10–/– mouse models." (PMID 34744620, 2021).
fibromatosis (1 paper, 2022). A poorly circumscribed neoplasm arising from the soft tissues. "Fibromatosis (Fibr) served as a pathological negative control, and STAT6 and CD34 staining was absent in the respective tissue sample." (PMID 36428694, 2022).
Graves disease (1 paper, 2016). Graves' disease is an autoimmune disorder that leads to overactivity of the thyroid gland (hyperthyroidism).It is caused by an abnormal immune system response that causes the thyroid gland to produce too much thyroid hormones. "However, little is known regarding the STAT6 phosphorylation status in Graves' disease (GD) and its role in thyroid epithelial cells (TECs)." (PMID 27906181, 2016).
Headache (1 paper, 2018). Cephalgia, or pain sensed in various parts of the head, not confined to the area of distribution of any nerve. "It is worth noting that many nearby supporting SNPs for the LRP1 region were located in the nearby gene of STAT6 (which was also strongly associated with headache)." (PMID 29397368, 2018). "It is also interesting to note that the STAT6 gene was the most significant in the gene analysis with headache and not the LRP1 gene where the top SNP resides." (PMID 29397368, 2018).
Heartburn (1 paper, 2024). "Heartburn incidence was higher in patients with the STAT6 rs167769 G/G genotype compared to G/A (54.55% vs. 11.77%, p = 0.030)." (PMID 38612496, 2024). "Heartburn incidence was higher in STAT6 rs167769 (g.27148G>A) G/G patients compared to G/A (54.55% vs. 11.77%, p = 0.030)." (PMID 38612496, 2024). "Also, a tendency towards higher heartburn incidence in the STAT6 rs324011 G/G genotype compared to G/A + A/A genotypes (50.00% vs. 16.67%, p = 0.091), and in the STAT6 rs12368672 G/G genotype compared to the G/C + C/C genotypes (46.15% and 13.33%, p = 0.096), was observed." (PMID 38612496, 2024).
HIV-1 infection (1 paper, 2025). The type species of lentivirus and the etiologic agent of acquired immunodeficiency syndrome (AIDS). "Nevertheless, given the clinical relevance of Kaposi’s sarcoma (KS) as a major complication of HIV-1 infection, and considering that STAT6 has been implicated in the regulation of Kaposi sarcoma–associated herpesvirus (KSHV) activity, it is important to discuss STAT6 in this context." (PMID 41009690, 2025). "To date, no studies have specifically addressed whether HIV-1 infection directly alters STAT6 activation, signaling, or regulation, and thus evidence on this point is currently lacking in the scientific literature." (PMID 41009690, 2025).
Huntington disease (1 paper, 2025). Huntington disease (HD) is a rare neurodegenerative disorder of the central nervous system characterized by unwanted choreatic movements, behavioral and psychiatric disturbances and dementia. "Examples include the exoASOTM platform from Codiak BioSciences, which targets transcriptional regulators like STAT6 in tumor-associated macrophages, and Evox Therapeutics’ genome-editing exosomes, developed for disorders like Spinocerebellar Ataxia 2 and Huntington’s disease." (PMID 41155971, 2025).
hyperreactivity (1 paper, 2022). "Interference with STAT6 can effectively prevent the development of the main features of allergic airway diseases, such as allergen-induced airway inflammation and airway hyperreactivity." (PMID 35204186, 2022).
hypersplenism (1 paper, 2024). Overactive functioning of the spleen, resulting in excessive destruction of blood cells. "The expression of SCARB1, ALOX15, STAT6, and IL4 was up-regulated in hypersplenism, while the PPARγ expression was down-regulated." (PMID 39620221, 2024).
hypertensive heart disease (1 paper, 2022). Abnormal enlargement of the heart resulting from long-standing hypertension. "Regarding natural compounds, for instance, celastrol alleviated hypertensive heart disease and cancer metastasis through inhibiting STAT3 and STAT6 signaling, respectively." (PMID 36324680, 2022).
iron deficiency (1 paper, 2018). "Indeed, the gene expression of Arg1, Ym1, IL-10 and Stat6, a series of genes expressed in M2 polarized macrophages, was increased after high iron diet condition, and, conversely, the expression of Arg1 and IL-10 was significantly decreased after dietary iron deficiency." (PMID 29771935, 2018).
lower respiratory tract infection (1 paper, 2022). "Luteolin helped treat acute lower respiratory tract infection by activating STAT1 and alleviating inflammation through both inhibiting STAT3 and activating STAT6." (PMID 36324680, 2022).
lung tumor (1 paper, 2019). "At 4, 6, and 9 months after urethane injection, lung tumors were harvested from the STAT6−/− and WT mice for analysis." (PMID 31798581, 2019). "As STAT6 is mainly expressed in immune cells such as CD11b+ cells, we hypothesize that the depletion of STAT6 signaling affects lung tumor cell proliferation through interaction with the TME." (PMID 31798581, 2019). "We observed that knockdown of the STAT6 gene in several lung tumor cell lines (A549, H1299, SPC-A-1, and LLC1) resulted in no obvious change in tumor cell activity in vitro." (PMID 31798581, 2019).
march (1 paper, 2020). "Genome-wide association study (GWAS) data have indicated that EoE shares some susceptible genetic loci with other manifestations of the atopic march, including polymorphisms in the signal transducer and activator of transcription 6 gene (STAT6) and TSLP." (PMID 32973790, 2020).
Myocardial fibrosis (1 paper, 2020). "The microarray data revealed that the level of β1-AR expression in the spleen-derived CD11b+ cells of STAT6-KO mice was significantly higher than that of WT mice in a sensitive myocardial fibrosis model induced by MI." (PMID 33192584, 2020). "STAT6 deficiency further aggravated ISO-induced increased expression of α-SMA in cardiac fibroblasts, myocardial fibrosis, and cardiac dysfunction." (PMID 33192584, 2020).
myofibroblastoma (1 paper, 2022). A benign, well circumscribed soft tissue neoplasm characterized by the presence of spindle shaped myofibroblasts and mast cells in a collagenous stroma. "A perioperative immunohistochemical evaluation for diffuse and intense nuclear expression of STAT6 was helpful to distinguish SFT from myofibroblastoma." (PMID 36550858, 2022).
myopia (1 paper, 2024). "Eight pairs (protein-coding genes TOM1L2, MXRA7, RHPN2, and HINT1 for senile cataract, WARS1 and TDRD7 for AMD, STAT6 for myopia, and TPPP3 for DR) are newly reported in this study." (PMID 39408566, 2024).
nephritis (1 paper, 2022). Inflammation of renal tissue. "Similarly, administration of IL-4 neutralizing antibodies or deletion of STAT6 in NZM2410 mice resulted in the abrogation of nephritis symptoms." (PMID 35444658, 2022).
neural tumours (1 paper, 2025). "Although OFM lacks specific immunohistochemical markers, IHC is useful for excluding other myxoid lesions—S-100 helps rule out neural tumours, while CD34, STAT6, and BCL2 assist in excluding myxoid solitary fibrous tumour." (PMID 41283480, 2025).
neurocysticercosis (1 paper, 2021). "Recent work has described a critical role for STAT-6 in the upregulation of the alternative activation markers, which is required for controlling M. corti-induced neurocysticercosis." (PMID 33461599, 2021).
Non-alcoholic Fatty Liver Disease (1 paper, 2024). "Furthermore, overexpression of SNHG20 stimulates the activation of STAT6, induces M2 polarization of hepatic KCs, and promotes Non-alcoholic Fatty Liver Disease (NAFLD) progression to HCC." (PMID 38523627, 2024).
osteoarthritis (1 paper, 2023). A noninflammatory degenerative joint disease occurring chiefly in older persons, characterized by degeneration of the articular cartilage, hypertrophy of bone at the margins and changes in the synovial membrane. "Furthermore, in osteoarthritis synovial cells, IL-13 activated signal transducer and activator of transcription 6 (STAT6) to upregulate POSTN expression." (PMID 38020106, 2023).
pancreatitis (1 paper, 2026). Inflammation of the pancreas. "STAT6-signaling directly stimulated the production of selected extracellular matrix components in pancreatitis associated fibroblasts (PAFs)." (PMID 41486955, 2026).
pemphigoid (1 paper, 2022). "The increase of STAT6 expression in biopsies of BP patients can also be explained by both the involvement of the Th2 response in the pathogenesis of pemphigoid and the specific eosinophilic cytokine profile present in this disease entity." (PMID 36613766, 2022).